ATXN2 (ataxin 2)
Description:
Involved in EGFR trafficking, acting as negative regulator of endocytic EGFR internalization at the plasma membrane.
Synonyms: ATX2; SCA2; TNRC13
Tractability: PROTAC: UniProt records ubiquitination sites on it; ubiquitination databases record sites on it; its protein half-life has been measured.
Gene: Protein-coding gene on chromosome 12 (111,443,485 to 111,599,676, reverse strand). Ensembl gene ENSG00000204842.
Subcellular location: Cytoplasm
Subcellular location (Human Protein Atlas): Cytosol
Gene Ontology:
Molecular function: epidermal growth factor receptor binding; protein binding; RNA binding
Biological process: negative regulation of receptor internalization; P-body assembly; stress granule assembly; regulation of translation; RNA metabolic process; RNA transport
Cellular component: cytoplasm; cytoplasmic stress granule; Golgi apparatus; membrane; perinuclear region of cytoplasm; ribonucleoprotein complex; trans-Golgi network
Genetic constraint (gnomAD): Loss-of-function variants: 23 observed, 102.08 expected, observed/expected ratio (o/e) 0.23, 90% interval 0.16 to 0.32. The upper end of that interval is the gene's LOEUF score, 0.32, which puts it in group 1 of 6, group 1 being the genes least tolerant of losing a copy. Missense variants: 1,040 observed, 1,295.2 expected, observed/expected ratio (o/e) 0.8, 90% interval 0.76 to 0.85. Synonymous variants: 462 observed, 471.73 expected, observed/expected ratio (o/e) 0.98, 90% interval 0.91 to 1.06.
Gene-disease validity (ClinGen):
ClinGen rates the evidence that ATXN2 causes each of these diseases.
spinocerebellar ataxia type 2 (autosomal dominant): Definitive. A subtype of type I autosomal dominant cerebellar ataxia (ADCA type I) characterized by truncal ataxia, dysarthria, slowed saccades and less commonly ophthalmoparesis and chorea.
Homologues: Orthologues: chimpanzee ATXN2 (99% identical), macaque ATXN2 (98% identical), dog ATXN2 (95% identical), pig ATXN2 (94% identical), guinea pig ATXN2 (94% identical), mouse Atxn2 (91% identical), rat Atxn2 (91% identical), rabbit ATXN2 (87% identical), tropical clawed frog atxn2 (74% identical), zebrafish atxn2 (61% identical), Caenorhabditis elegans atx-2 (18% identical). Paralogues in human: ATXN2L (37% identical).
Diseases named in the same sentence as ATXN2 in open-access papers:
ATXN2 is named in the same sentence as 148 diseases in open-access papers, as found by Europe PMC text mining. Sharing a sentence is not in itself a finding about the gene and the disease. The quoted sentences say what the papers report.
spinocerebellar ataxia type 2 (144 papers, 2009 to 2026). "In connection to neurodegenerative disease, polyglutamine (polyQ) repeat expansions in ATXN2 cause spinocerebellar ataxia type 2 (SCA2) and increase the risk for development of ALS." (PMID 41397872, 2026). "Spinocerebellar ataxia type 2 (SCA2) is an autosomal dominant neurodegenerative disorder caused by a pathogenic CAG trinucleotide repeat expansion in the ATXN2 gene." (PMID 41683965, 2026). "ATXN2 repeat expansions were initially associated with spinocerebellar ataxia type 2 (SCA2); however, based on repeat length, they later became associated with other neurodegenerative diseases." (PMID 40565515, 2025). "Two amyotrophic lateral sclerosis patients in our cohort carried ≥33 repeats in ATXN2, a cause of spinocerebellar ataxia type 2." (PMID 38585669, 2024). "Two patients carried expanded ATXN2 alleles in the range associated with reduced penetrance for spinocerebellar ataxia type 2 (33 and 34 repeats)." (PMID 38585669, 2024). "On the other hand, the malfunctioning of ATXN2 has been associated with many diseases, especially spinocerebellar ataxia type 2 (SCA2) and amyotrophic lateral sclerosis (ALS), but also parkinsonism, SCA1, SCA3, obesity, and diabetes." (PMID 38877004, 2024). "Spinocerebellar ataxia type 2 (SCA2) is a polyglutamine disorder caused by a pathological expansion of CAG repeats in ATXN2 gene." (PMID 37537226, 2023). "Spinocerebellar ataxia 2 (SCA2) is a neurodegenerative disorder caused by the expansion of the poly-glutamine (polyQ) tract of Ataxin-2 (ATXN2)." (PMID 38128014, 2023). "Spinocerebellar ataxia type 2 (SCA2) is an autosomal dominant neurodegenerative disorder caused by a pathological expansion of polyglutamine in the ataxin-2 protein." (PMID 37537226, 2023). "Ataxin-2 is a polyglutamine (polyQ) protein in which long (>34) polyQ expansions cause spinocerebellar ataxia 2 (SCA2), and intermediate-length repeats are a risk factor for ALS." (PMID 36288714, 2022). "In drosophila, mutant ataxin-2 (causing spinocerebellar ataxia type 2) disrupts Ago expression and miRNA function." (PMID 35869509, 2022). "In terms of the present review, the most interesting protein is ATXN2, as the expanded repeat tract in ATXN2 is responsible for spinocerebellar ataxia type 2 (SCA2), as well as normal ATXN2 is implicated in amyotrophic lateral sclerosis (ALS)." (PMID 35203324, 2022). "We focused on specific candidates: ATXN2, whose polyQ expansions cause spinocerebellar ataxia 2 (SCA2), and GEMIN5, whose biallelic mutations cause neurodevelopmental delay and ataxia." (PMID 36136249, 2022). "In particular, spinocerebellar ataxia type 2 (SCA2) is due to a CAG repeat expansion mutation in the ATXN2 gene and it reaches the highest worldwide prevalence in Holguín province, Cuba." (PMID 33688396, 2021). "Spinocerebellar ataxia type 2 (SCA2) is caused by an abnormal expansion of CAG repetition (>33) in the ATXN2 gene, coding for Ataxin2 protein, with an estimated prevalence in certain areas of 6.57 cases per 100,000 individuals." (PMID 33733696, 2021). "Spinocerebellar ataxia type 2 is a polyglutamine (polyQ) disease associated with an expanded polyQ domain within the protein product of the ATXN2 gene." (PMID 34077532, 2021). "The human ortholog of Pbp1, Ataxin-2, has been linked to many neurodegenerative diseases: mutations within Ataxin-2 such as poly(Q) expansion has been linked to the pathology of spinocerebellar ataxia type 2." (PMID 33984024, 2021). "Spinocerebellar ataxia type 2 is caused by CAG expansions in the gene ataxin-2 (ATXN2), which is an RNA-binding protein that interacts with the poly (A)-binding protein and regulates mRNA stability." (PMID 33671313, 2021). "Spinocerebellar ataxia type 2 (SCA2) is a dominantly inherited rare polyglutamine disease caused by a CAG repeat expansion in the ataxin-2 (ATXN2) gene." (PMID 32307524, 2020).
spinocerebellar ataxia type 2 (continued). "Whereas the CAG-expansion in ATXN2 causes spinocerebellar ataxia 2, an interrupted expansion of the polyglutamine stretch is responsible for the development of PD." (PMID 32630630, 2020). "Similar changes in Purkinje neuron activity were observed in another ataxia animal model, the ataxin 2 (Atxn2) mouse carrying a mutation of ataxin 2 [ATXN2Q127: Tg(Pcp2-ATXN2*127Q)#Plt/0] found in patients with spinocerebellar ataxia type 2." (PMID 32954283, 2020). "Ataxin-2 is a cytosolic SG protein that is associated with the neurodegenerative disorder spinocerebellar ataxia type-2 (SCA2)." (PMID 30944179, 2019). "Mutations in TDP-43 or FUS lead to ALS/FTD, while mutations in Ataxin-2 can cause spinocerebellar ataxia type 2 or ALS." (PMID 31138677, 2019). "Atx-2 is an RNA-binding protein related to neurodegeneration since mutations resulting in the expansion of a polyglutamine tract in the gene encoding ataxin-2 give rise to the neurodegenerative disorders spinocerebellar ataxia type 2 and Parkinson’s disease." (PMID 31191246, 2019). "Spinocerebellar ataxia type 2 (SCA2) is caused by the abnormal expansion of Cytosine-Adenine-Guanine (CAG) triplet repeats in the coding region of the ataxin-2 gene (12q24.1)." (PMID 31547441, 2019). "Spinocerebellar ataxia type 2 (SCA2) is a neurodegenerative disease caused by expansion of polyglutamine tract in the ATXN2 protein." (PMID 30194296, 2018). "From these screens many previously undescribed genetic interactions of TDP-43 have been identified, the most significant being the modulation of TDP-43 toxicity by ATAXIN-2 (ATXN2), the polyQ protein mutated in spinocerebellar ataxia type 2 (SCA2)." (PMID 30425620, 2018). "ATXN2 polyglutamine expansion drives neurodegeneration causing spinocerebellar ataxia type 2 and promoting amyotrophic lateral sclerosis." (PMID 30417124, 2018). "The ATXN2L protein is a paralog of ataxin-2 which has been implicated in the neurodegenerative disorder spinocerebellar ataxia type 2." (PMID 29262599, 2017). "ATXN2 (OMIM:601517) is associated with Spinocerebellar ataxia 2, susceptibility to Amyotrophic lateral sclerosis, susceptibility to Parkinson disease and late-onset." (PMID 29291004, 2017). "For example, ATXN2 encodes a polyglutamine protein associated with spinocerebellar ataxia 2 and contains an expansion that also confers increased susceptibility to ALS in sporadic, and possibly C9, cases." (PMID 27623008, 2016). "Spinocerebellar ataxia type 2 (SCA2) is an autosomal dominant ataxia caused by an expansion of CAG repeats in the exon 1 of the gene ATXN2, conferring a gain of toxic function that triggers the appearance of the disease phenotype." (PMID 28018166, 2016). "Spinocerebellar Ataxia Type 2 (SCA2) is caused by an expanded CAG trinucleotide repeat in the gene ATXN2 encoding the protein ataxin-2." (PMID 26263162, 2015). "High CAG repeat expansions (usually greater than 34) in coding regions of the ATXN2 gene are the cause of spinocerebellar ataxia type 2 (SCA2), transmitted in an autosomal dominant manner." (PMID 25148523, 2014). "Expansions of the polyglutamine (polyQ) domain (≥34) in Ataxin-2 (ATXN2) are the primary cause of spinocerebellar ataxia type 2 (SCA2)." (PMID 22916186, 2012). "Expansion of a CAG repeat in the ataxin-2 protein causes the neurodegenerative disease spinocerebellar ataxia type 2." (PMID 22022282, 2011). "In this study the transcript of Ataxin 2, a protein mutated in spinocerebellar ataxia type 2 (SCA2), had a fold change of 1.24 by microarray analysis; certainly suggesting a link between its expression and the overexpression of Rai1." (PMID 21629438, 2010). "Spinocerebellar ataxia type 2 (SCA2) is an autosomal dominant disease caused by the increment of a CAG repeat tract in ataxin-2 gene, generating an expanded polyglutamine tract in this protein." (PMID 21629438, 2010).
spinocerebellar ataxia type 2 (continued). "Interestingly, ATXN2 with intermediate PolyQ repeats is associated not only with spinocerebellar ataxia type 2 (SCA2), but also with ALS, serving as a risk factor for C9ORF72-linked ALS." (PMID 37006471, 2023). "Spinocerebellar ataxia type 2 (SCA2) is caused by a CAG expansion in ataxin-2 (ATXN-2)." (PMID 32264890, 2020). "Spinocerebellar ataxia type 2 (SCA2) is caused by polyglutamine repeats in the ATXN2 protein." (PMID 30194296, 2018). "Proline-rich motifs that may mediate protein interactions are widespread in Ataxin-2 proteins, but expansion of polyglutamine tracts associated with spinocerebellar ataxia type 2, is present only in primates, as well as some insects." (PMID 25027299, 2014). "In addition, CpG methylation in human ATXN2 gene promoter is associated with pathogenic CAG expansions in spinocerebellar ataxia type 2 (SCA2) cases." (PMID 24367332, 2013). "For the disease-causing protein in spinocerebellar ataxia type 2, ataxin-2, a paralog of unknown function, termed ataxin-2-like, has been described." (PMID 23209657, 2012). "Expansion of a CAG repeat of the ATXN2 gene causes spinocerebellar ataxia type 2." (PMID 23157318, 2012). "Spinocerebellar ataxia 2 (SCA2) is an autosomal dominant disease caused by an expanded CAG trinucleotide repeat encoding glutamine within the open reading frame of the gene encoding the ataxin 2 protein, ATAXIN2 (ATXN2)." (PMID 21479228, 2011). "Dysregulation or mutation of the Ataxin-2 gene (ATXN2) can lead to neurodegenerative diseases such as spinocerebellar ataxia type 2 (SCA2) and amyotrophic lateral sclerosis (ALS)." (PMID 41462986, 2025). "Expansion of the CAG repeats above 44 in the ATXN1 gene causes spinocerebellar ataxia type 1 (SCA1), while more than 35 CAG repeats in the ATXN2 gene is the cause of spinocerebellar ataxia type 2 (SCA2)." (PMID 41149812, 2025). "The ATXN2 gene, linked to neurodegenerative disorders like spinocerebellar ataxia type 2 (SCA2), is known to exhibit age-dependent increases." (PMID 40943361, 2025). "In the present study, we aimed to identify molecular features of small-molecule compounds capable of inhibiting the expression of the ataxin-2 (ATXN2) gene, which is implicated in Spinocerebellar Ataxia Type 2 (SCA2)." (PMID 40427711, 2025). "Spinocerebellar ataxia type 2 (SCA2) is a polyglutamine disorder, and variants in its disease protein Ataxin-2 act as modifiers in the progression of Amyotrophic Lateral Sclerosis." (PMID 41298695, 2025). "The CAG repeat expansion in ATXN2 with repeat lengths of ≥35 CAG repeats is a cause of spinocerebellar ataxia type 2 (SCA2)." (PMID 38891021, 2024). "Ataxin-2 (ATXN2) is a causative gene in spinocerebellar ataxia type 2 (SCA2), an inherited neurodegenerative disease caused by the expansion of the CAG trinucleotide repeat encoding polyglutamine (polyQ) within the ATXN2 gene." (PMID 38869059, 2024). "Although overexpanded ATXN2 is predominantly linked to spinocerebellar ataxia type 2 (SCA2), intermediate expansions are also implicated in amyotrophic lateral sclerosis (ALS) and parkinsonism." (PMID 38877004, 2024). "Mutations in the human Ataxin2 (ATXN2) gene lead to spinocerebellar ataxia type 2 (SCA2) which accounts for 13% of spinocerebellar ataxias." (PMID 37274187, 2023). "Spinocerebellar ataxia type 2 (SCA2) is an autosomal dominantly inherited neurodegenerative disease which is caused by the expansion of the triplet CAG in exon 1 of the ATXN2 gene localized on chromosome 12q24." (PMID 36894829, 2023). "CAG repeat expansions in the ATXN2 (ataxin-2) gene can cause the autosomal dominant disorder spinocerebellar ataxia type 2 (SCA2) as well as increase the risk of ALS." (PMID 35787375, 2022). "ATXN2 pathological expansion of trinucleotides is linked to familial spinocerebellar ataxia type 2 (SCA2), but it is also a risk factor for ALS, and it is linked to TDP-43 proteinopathy." (PMID 36555161, 2022).
spinocerebellar ataxia type 2 (continued). "Expansions of ATXN2 polyQ repeats (from the physiological 22 copies to more than 33) cause spinocerebellar ataxia type 2 (SCA-2;), an autosomal-dominant disorder mainly impairing cerebellar neuron circuits." (PMID 34638636, 2021). "Beyond C9ORF72, studies have identified CAG repeat expansion in the ataxin-2 gene (ATXN2) as a genetic cause of spinocerebellar ataxia type 2 (SCA2) and ALS." (PMID 33732107, 2021). "The pathogenic role of ATXN2 in human disease was first reported in familial spinocerebellar ataxia type 2 (SCA2) cases, in which the mutant allele of ATXN2 harboring highly expanded CAG/CAA repeats (> 34) was found." (PMID 33115537, 2020). "Spinocerebellar ataxia type 2 (SCA2) is an autosomal-dominantly inherited neurodegenerative disorder, caused by repeat expansion mutations in the ataxin-2 (ATXN2) poly-glutamine domain (polyQ, encoded by CAG repeats at the DNA level)." (PMID 32932600, 2020). "Long (more than 33) CAG repeat expansion in ATXN2 gene has been identified as a cause of spinocerebellar ataxia type 2 (SCA2)." (PMID 26843957, 2016). "Spinocerebellar ataxia type 2 (SCA2) is a progressive autosomal dominant disorder caused by the expansion of a CAG tract in the ATXN2 gene." (PMID 26086378, 2015). "For example, patients carrying a pathogenic allele of Ataxin-2 causing Spinocerebellar Ataxia Type 2 (SCA-2) experience sleep disruptions prior to suffering from ataxic symptoms." (PMID 26068245, 2015). "Pathogenic CAG repeat expansion in the ataxin-2 gene (ATXN2) is the genetic cause of spinocerebellar ataxia type 2 (SCA2)." (PMID 23936447, 2013). "Recent reports showed that the human ataxia type 2 (ATXN2) gene, a polyglutamine disease gene mutated in spinocerebellar ataxia type 2 (SCA2), was associated with an increased risk for ALS." (PMID 22013437, 2011). "Expansion of a CAG repeat in the coding region of exon 1 in the ATXN2 gene located in human chromosome 12q24.1 causes the neurodegenerative disease spinocerebellar ataxia type 2 (SCA2)." (PMID 20016785, 2009). "Polyglutamine expansion in Ataxin-2 (ATXN2) is responsible for rare, dominantly inherited Spinocerebellar Ataxia type 2 (SCA2)." (PMID 41683920, 2026). "Ataxin 2 (ATXN2), an RBP that when mutated by polyglutamine (polyQ) expansion causes spinocerebellar ataxia type 2 (SCA2), was shown to bind to the amyotrophic lateral sclerosis (ALS)–linked Tar DNA-binding protein 43 (TDP-43)." (PMID 39955058, 2025). "Evox is developing therapies for diseases with well-defined genetic drivers, including Spinocerebellar Ataxia type 2 (SCA2) via ATXN2 targeting, and Huntington’s disease through MSH3 suppression, with potential relevance to other repeat expansion disorders." (PMID 41155971, 2025). "Spinocerebellar ataxia type 2 (SCA2) and amyotrophic lateral sclerosis (ALS) are both associated with a CAG-repeat expansion in ATXN2 and with TDP-43-positive neuronal cytoplasmic inclusions." (PMID 39956874, 2025). "Ataxin-2 (ATXN2) was originally discovered in the context of spinocerebellar ataxia type 2 (SCA2), but it has become a key player in various neurodegenerative diseases." (PMID 39039334, 2024). "Spinocerebellar Ataxia Type 2 (SCA2) is caused by an expansion of the CAG codons within the exons of the ATXN2 gene, which produces the ataxin-2 protein." (PMID 38921455, 2024). "Recent research has expanded our understanding of ATXN2's role in neurodegenerative diseases, particularly in the context of spinocerebellar ataxia type 2 (SCA2)." (PMID 39039334, 2024). "Spinocerebellar ataxia type 2 (SCA2) is a rare polyglutamine-dependent NDD affected by a CAG repeat expansion in the ataxin-2 gene." (PMID 35093121, 2022). "Mutations in the ataxin-2 gene (ATXN2) cause the neurodegenerative disorders amyotrophic lateral sclerosis (ALS) and spinocerebellar ataxia type 2 (SCA2)." (PMID 36288714, 2022).